IL32 (interleukin 32)
Diseases named in the same sentence as IL32 in open-access papers (continued):
Sharing a sentence is not in itself a finding about the gene and the disease.
tumor (continued). "To assess the functional relevance of cross-presenting cDC1 in IL-32–induced tumor control, we examined the effects of IL-32 treatment in B16F10 tumors inoculated in Batf3–/– mice according to the established treatment regimen." (PMID 32841222, 2020). "In ESCC, IL32 expression and Treg infiltration were found to play an important synergistic role in tumor growth and invasion; the combination of which was one of poor independent factors." (PMID 32454908, 2020). "Deficiency of cross-presenting DC (in Batf3–/– mice) or CD8+ T cells abrogated the therapeutic efficacy of IL-32 in mice, suggesting that the IL-32 effector mechanisms are dependent on cDC1 priming of tumor-specific CD8+ T cells." (PMID 32841222, 2020). "Mice receiving both IL-32 and anti–PD-1 showed significantly reduced tumor growth compared with mice receiving either monotherapy and displayed the most significant increase in CD45+ leukocytes." (PMID 32841222, 2020). "The capacity of IL-32 to control tumor growth was abrogated in Batf3–/– mice, both in the primary and untreated contralateral tumors." (PMID 32841222, 2020). "Together with the serum cytokine profiling, these data suggest IL-32 as a safe tumor treatment and suggest that it is also safe when combined with anti–PD-1 therapy." (PMID 32841222, 2020). "The IL-32 concentration in tumor (p < 0.00001) and adjacent tissue (p < 0.00001) as well as fold-change in concentration (tumor-to-adjacent) were significantly lower in CRC as compared to GC and ESCC." (PMID 33020452, 2020). "Cytokines regulating PD-L1 expression, including IFN-g, IL-1a, IL-10, IL-27 and IL-32 g, signal through diverse transcription factors and have variable effects on tumor cells and Monos." (PMID 31730010, 2019). "In the tumor microenvironment, IL32 expression is highly correlated with genes related to T cell infiltration, and also positively correlates with high AXL/low MITF dedifferentiated gene signature." (PMID 30953519, 2019). "In our recent studies, IL-32 inhibited tumor growth in a xenograft animal model and carcinogen-induced colon tumor development." (PMID 29467412, 2018). "The ASE genes that was mostly recurrently observed in both tumor and normal samples had a high allele imbalance, such as AP3P1, BCLAF1, STED8, PRIM2, IL32, SEC22, and MAP2K3." (PMID 30538721, 2018). "Various isoforms of IL-32 are produced by alternative splicing mechanism and there are conflicting observations of either an oncogenic or a tumor suppressive role for IL-32." (PMID 29050245, 2017). "Not only does IL-1B appear positively correlated with MAP17 in all tumors, other interleukins including IL-15, IL-18, IL-1A, IL-32 and IL-7 and interleukin receptors including IL-10RB, IL-17RC and IL-2RG appear in at least three of the tumor types." (PMID 29228712, 2017). "Another cytokine, IL-32, has been recently proposed as lung adenocarcinoma prognostic biomarker, as its overexpression in the tumor tissue correlates with a greater number of lymph node metastases." (PMID 27445423, 2016). "Several tumor suppressor genes, including E-cadherin, IL-24, IL-32 and p21 have been reported to be activated by miRNAs through targeting specific sites in their promoters." (PMID 27429046, 2016). "It was revealed that IL-32 treatment at 0.2 mg/kg and 1 mg/kg increased the tumor graft growth compared with treatment with saline only." (PMID 25435980, 2015). "Anti-tumor activity of NK cells is provoked by IL-12 and IL-18, both of which induce IL-32 production that stimulates TNF-α synthesis enhancing NK apoptotic activity." (PMID 25626592, 2015). "IL-32 expression in tumor cells has been confirmed mainly occurring in the advanced stages of cancers." (PMID 25889282, 2015). "The effects of IL-32 on tumor cell growth in cell cuture and a tumor xenograft model were investigated, as well as the effects of IL-32 on apoptosis." (PMID 25435980, 2015).
tumor (continued). "The results revealed that IL-32 increases the proliferation rate of cancer cells and decreases the rate of apoptosis, In addition, IL-32 was found to enhance the growth of tumor xenografts in vivo." (PMID 25435980, 2015). "Interleukin-32 (IL-32) is a cytokine involved in a broad repertoire of immunopathological events across both physiological and disease contexts, encompassing immune modulation, inflammatory amplification, and tumor initiation and progression." (PMID 41685297, 2026). "Even IL32, which is traditionally viewed as a pro-inflammatory cytokine, may in this context contribute to tumor progression through stromal crosstalk." (PMID 40723289, 2025). "It was unclear whether PCs are the source of IL32 in the tumor microenvironment and whether this is correlated with cancer progression." (PMID 39435643, 2024). "In addition, tumor stemness, TMB, MSI, and immune checkpoint genes were also associated with IL32 expression." (PMID 38584169, 2024). "Tumor tissues had higher IL32 expression levels than normal tissues." (PMID 38584169, 2024). "Also, the IL-32 isoforms α, β, and γ also play essential roles in regulating the anti-tumor immune response." (PMID 38607023, 2024). "Clinical evidence, supported by single‐cell RNA sequencing and multiplex immunostaining of tumor tissues, confirms the presence of IL32‐expressing pericytes closely interacting with β5‐integrin‐expressing cancer cells in EGFR‐mutated patients, impacting therapeutic response and prognosis." (PMID 39435643, 2024). "Furthermore, IL-32 is secreted by MM cells in exosomes and alters the tumor microenvironment by promoting osteoclastogenesis and bone degradation as well as immune suppression." (PMID 36875074, 2023). "Meanwhile, tumor cells are also the main source of IL-32 in the process of neoplasia." (PMID 35428295, 2022). "Interestingly, the TIGIT+ Tregs also highly expressed IL‐32 which further promoted the migration and invasion of tumor cells." (PMID 35474948, 2022). "Interestingly, a pro-inflammatory cytokine IL32 is highly expressed in ESCC tumor tissues, and the IL32 derived from ESCC extracellular vesicles plays a key role in promoting lung metastasis by inducing M2-Mø polarization via the FAK-STAT3 pathway." (PMID 36211375, 2022). "However, better characterization of the tumor microenvironment is needed to understand how different cell types in the tumor microenvironment are influenced by IL-32." (PMID 35281008, 2022). "Our results suggested that tumor cell was the main source of IL-32." (PMID 35428295, 2022). "The results showed that IL-32 was able to promote tumor growth." (PMID 35428295, 2022). "TIGIT+ Tregs highly expressed IL‐32 and promoted the migration and invasion of tumor cells." (PMID 35474948, 2022). "Therefore, IL-32 resulted in reducing tumor growth and rendering immune checkpoint blockade resistance." (PMID 35281008, 2022). "In addition, a recent study has demonstrated that IL-32 enhanced the anti-tumor activity by promoting IFN-γ expression in CD8+ T cells, while suppressing the immune responses by inducing Foxp3+ Tregs cells, indicating its contradictory role in the TME of ESCC." (PMID 36698392, 2022). "IL-32 was found to play two contradictory roles in cancer development among various cancer types, one role as a critical proliferation and growth factor and the other as a tumor suppressor." (PMID 35281008, 2022). "The results also showed that IL-32 was expressed higher in tumor tissues (P < 0.001)." (PMID 35428295, 2022). "Importantly, our immunohistochemical results clearly showed that IL-32 was mainly expressed in the cytoplasm of the tumor cell, and was significantly higher in the tumor nest compared with the non-cancerous tissue." (PMID 35428295, 2022). "However, the role and the significance of IL-32 in infiltrating Treg cells in the tumor microenvironment (TME) still need to be explored." (PMID 34414188, 2021).
tumor (continued). "However, what types of tumor-infiltrating lymphocytes express IL-32 and the exact role of IL-32 in these cells are still unclear and need further study." (PMID 34414188, 2021). "Although various biological activities of IL-32 in tumor progression have been reported, a comprehensive analysis is required in clinical studies along with in vitro and in vivo studies because IL-32 has dual effects in tumor biology, such as procancer effects and anticancer effects." (PMID 34682815, 2021). "In addition, CAF-derived interleukin-32 promotes tumor cell invasion and metastasis by activating the p38 mitogen-activated protein kinase signaling." (PMID 34572878, 2021). "Besides, the combination of IL-32 expression on tumor cells and Treg infiltration was selected as the independent prognostic factor in ESCC." (PMID 34414188, 2021). "We further evaluated the IL-32 expression in the tumor and adjacent tissues T cell subsets." (PMID 34414188, 2021). "It is hypothesized that IL-15 promotes tumor progression via induction of survival and anti-apoptotic signals in malignant T-cells, while IL-32 has been shown to accelerate the proliferation of CTCL cell lines through MAPK and NF-KB dependent mechanisms." (PMID 34204115, 2021). "In NK cells, the cytotoxic and exhausted subset IL-32 expression was much higher in tumor tissue." (PMID 34414188, 2021). "IL-32 has been known to affect tumor death by regulating immune cells including NK cells." (PMID 34682815, 2021). "Similarly, IL-6 and IL-32 participate in the immunosuppressive regulation of the tumor microenvironment." (PMID 34349753, 2021). "We further analyzed IL-32 expression between the tumor and adjacent tissues." (PMID 34414188, 2021). "In fact, IL32 was mainly detected in activated NK cells and dendritic cells (DCs), which induce tumor cell apoptosis by producing cytolytic molecules such as perforin and granzyme from activated NK cells in tumor environments." (PMID 34682815, 2021). "In order to determine whether IL-32 treatment resulted in increased tumor antigen-reactive CD8+ T cells, we assessed their specificity for MHC class I tetrameric complexes bearing SVYDFFVWL peptides derived from tyrosinase-related protein 2 (TRP-2)." (PMID 32841222, 2020). "To assess whether an increase in the frequency of tumor-reactive CD8+ T cells is essential for IL-32–mediated control of tumor growth, we performed antibody-based depletion of CD8+ T cells in mice concurrently receiving IL-32." (PMID 32841222, 2020). "However, IL-32 treatment was more effective in the contralateral tumors, demonstrating its ability to induce potent systemic tumor immunity." (PMID 32841222, 2020). "Injection of IL-32 in murine tumors induced a systemic, tumor-specific immune response." (PMID 32841222, 2020). "IL-32 inhibits tumor growth via inhibition of NF-κB and STAT3 signals in colon and prostate cancer." (PMID 32308549, 2020). "Tumor expression of IL32 was the highest in ESCC and the lowest in CRC." (PMID 33020452, 2020). "Consequently, the fold-change in expression ratio (tumor-to-adjacent) was higher in left-sided CRCs, significantly so for IL32 transcripts." (PMID 33020452, 2020). "Ccr5 deficiency abrogated the IL-32–mediated CD8+ T cell infiltration and its therapeutic effect, i.e., tumor growth reduction, highlighting the induction of T cell–recruiting chemokines as a key effector mechanism of IL-32 in tumor immunity." (PMID 32841222, 2020). "To obtain a more comprehensive analysis of the changes induced by IL-32 within the TME and systemically, we analyzed primary B16F10 tumor homogenates and sera from IL-32– and PBS-treated mice for the expression of 44 key cytokines and chemokines using an addressable laser bead immunoassay (ALBIA)." (PMID 32841222, 2020). "Various published data demonstrated that IL32 promotes or decreases tumor development." (PMID 32308549, 2020). "Intravenous IL-32 administration showed a similar effect on tumor growth." (PMID 32841222, 2020).
tumor (continued). "IL32 expression by dedifferentiated tumor cells may contribute to a proinflammatory tumor microenvironment." (PMID 30953519, 2019). "Their data also showed that IL32 contributed to tumor progression in both cell lines." (PMID 28966727, 2017). "Finally, IL-32 plays an important role in the tumor microenvironment by inducing the secretion of inflammatory mediators, such as TNF-α, IL-1β, IL-6, IL-8, IL-18, and MIP-2, which are related to invasion and metastasis." (PMID 27445423, 2016). "Following the results of the cell proliferation assay, it was investigated whether IL-32 contributed to tumor growth in vivo." (PMID 25435980, 2015). "Notably, IL32 and BATF have been implicated in the immunosuppressive functions of tumor-infiltrating Tregs, suggesting that IL32+BATF+ Tregs in dogs may represent a regulatory subset relevant in cancer." (PMID 41488614, 2025). "Moreover, GLUD1 inhibited the protein expression of IL-32 in HCC tumor xenografts." (PMID 38587834, 2024). "Therefore, it is reasonable to speculate that the expression of IL32 may regulate the immune response of tumor immune cells and affect the prognosis of tumor patients." (PMID 38584169, 2024). "IL-32 is typically highly expressed in inflammatory diseases and various malignant tumors, inducing the release of cytokines and playing a crucial role in the formation of the inflammatory microenvironment, thereby promoting the growth, migration, and invasion of tumor cells." (PMID 38584169, 2024). "In this work, based on various cohorts, we assessed the correlations between GLUD1 with IL-32 gene expression levels in HCC tissues, between SYVN1 and LASP1 gene expression levels in HCC tissues, and between GLUD1 gene expression level and tumor size in HBV-associated HCC." (PMID 38587834, 2024). "In the cancer setting, MM cell-derived IL-32 may also have indirect effects on tumor progression." (PMID 36875074, 2023). "Thus, due to its direct effects on tumor cells and the induction of a pro-tumorigenic microenvironment, targeting IL-32 could be beneficial in a subgroup of patients." (PMID 37313466, 2023). "However, the relationship between tumor cell-derived IL-32 and macrophage in ESCC remain unclear and require further research, and the pathway involved in this process also remain unclear." (PMID 35428295, 2022). "Therefore, finding the exact function of the IL-32 isoform is still a sensitive consideration and may be influenced not only by its isoform but also with cancer type as well as the whole tumor microenvironment." (PMID 35281008, 2022). "Therefore, IL-32 has been studied for its tumor control direction in several cancer types." (PMID 35281008, 2022). "In summary, expression of IL-32 in ESCC tumor specimens was abnormally higher both in mRNA and protein levels, and the protein expression of IL-32 was positively correlated with lymph node metastasis, suggesting that overexpression of IL-32 may play an important role in the metastasis of ESCC." (PMID 35428295, 2022). "However, the specific pathway by which IL-32 mediates the migration and invasion of tumor cells remains unknown." (PMID 35069212, 2021). "Studies have shown that, in addition to MM cells, IL-32 is also produced by the extracellular vesicles (EVs) involved in tumour growth and maintenance, which occur under hypoxic stress conditions, which characterizes the tumour microenvironment and promotes tumour progression." (PMID 33808304, 2021). "Our preliminary in vitro studies indicated that IL32, in an IL32β and IL32γ isoform specific manner, can modulate the polarization of myeloid cells toward an M1-like macrophage phenotype with costimulatory molecule expression, lending additional support for its impact in the tumor microenvironment." (PMID 30953519, 2019). "Additionally, IL32 expression did not correlate with genes associated with disease progression, tumor cell invasion, and migration, such as CD155/PRV and MMP2." (PMID 30953519, 2019).
tumor (continued). "Additionally, activin A may be negatively regulated by interleukin-32 (IL-32), which promotes proliferation and endothelial cell function during tumor promotion." (PMID 25560921, 2014). "All of the mechanisms attributed to IL32 could to some degree affect tumor progression." (PMID 25100201, 2014). "Tumor-specific deep crypt secretory cells (tDCS, cluster 10) demonstrated elevated expression of TFF1, FABP1, CKB, PRAP1, IL32, GPRC5A, and SOD3, and were consistent with secretory lineage plasticity and immune or stress-associated signaling." (PMID 41282138, 2025). "Numerous studies have reported significant associations between the expression levels of inflammatory cytokines—including IL-6, CXCL9, TNF-α, IL-17A, and IL-32—and LUAD tumor stage, metastasis, and prognosis." (PMID 40136462, 2025). "IL-6 and IL-8 from chemoresistant CAFs enrich CSCs by creating niches, and IL-32 in CAFs binds integrin β3, activating p38 MAPK signaling, upregulating EMT markers, and promoting tumor invasion." (PMID 40230452, 2025). "Specifically, alterations in cytokines such as IL32, IL22, IL17F, IL17A, IL16, IL15, and HMGB1 can create an immunosuppressive tumor microenvironment in CTCLs to facilitate immune evasion and tumor progression." (PMID 39409988, 2024). "Our study emphasized the role of IL6high CAF on tumor cells for elevating level of various cytokine genes including IL6, IL32, IL33, CXCL1, CXCL3 and CXCL8, and oncogenic pathways, such as the Wnt and VEGF signaling pathways." (PMID 38892065, 2024). "Each tumor sample’s TMB was calculated, and correlation was assessed between IL32 expression and TMB." (PMID 38584169, 2024). "Research indicates that SELENOP+ Mac can promote anti-tumor immunity by highly expressing FOLR2, IL32, CD3D, and LTC4S and are therefore considered to have anti-tumor effects." (PMID 38755647, 2024). "A study observed that IL-32 was involved in MRS2, and interacted with STMN1+ mononuclear/macrophage cells, thereby inhibiting tumor development." (PMID 36937389, 2023). "In the present study, we analyzed the expression and pathological pattern of IL-32 via RNA microarray (84 paired ESCC tumor and peritumor tissues) and tissue microarray (56 paired ESCC tumor and peritumor tissues)." (PMID 35428295, 2022). "In the present study, we found that IL-32 was positively correlated to monocyte and M2 macrophage as well as co-localization with CD206 in ESCC tumor tissue." (PMID 35428295, 2022). "Interestingly, the effect of the tumor-activated versus control SCs on SCLC cell invasiveness was significantly higher, and this was associated with a higher level of expression of several genes, including the STAT3, SOCS3, BCL6, ELF3, IGF2, and IL32 genes, in SCLC cells." (PMID 36551618, 2022). "Next, we verified the relationship between IL-32 and M2 macrophages (CD206) in tumor and the paired peritumor tissues by IHC and IF." (PMID 35428295, 2022). "Therefore, we hypothesized that IL-32 may be enclosed in EV to change the tumor microenvironment." (PMID 35428295, 2022). "We next explored if depletion of IL-32 from the more aggressive and robust cell line JJN-3 affected tumor growth in vivo." (PMID 35005550, 2022). "Various cytokines, such as IL-13, IL-15, and IL-32, and surface proteins, including CD47, CD40, and CD28, provide the direct molecular bridge between tumor cells and adjacent cells, resulting in tumor progression." (PMID 34830466, 2021). "Therefore, we studied the relationship between IL-32 gene expression and tumor-infiltrating immune cells using quanTIseq, a recently described computational approach to estimate the relative proportions of various tumor infiltrating immune cells from bulk tumor RNA-Seq profiles." (PMID 32841222, 2020). "CAFs directly stimulate tumor cell migration and invasion through the secretion of TGF-β, IL-32, PDGF and FGF that induce EMT, actin polymerization/depolymerization and cell motility." (PMID 33114328, 2020).